MIR33A (microRNA 33a)
Synonyms: hsa-mir-33; hsa-mir-33a; MIR33; MIRN33; MIRN33A; miR-33; miRNA33A; mir-33a
Gene: MicroRNA gene on chromosome 22 (41,900,944 to 41,901,012, forward strand). Ensembl gene ENSG00000207932.
Gene Ontology:
Biological process: miRNA-mediated post-transcriptional gene silencing
Cellular component: RISC complex
Homologues: Orthologues: chimpanzee ptr-mir-33a (100% identical), macaque mml-mir-33a (97% identical), guinea pig MIR33A (91% identical), mouse Mir33 (91% identical), rat Mir33 (91% identical), dog MIR33A (86% identical), tropical clawed frog xtr-mir-33a (75% identical), Drosophila melanogaster mir-33 (62% identical). Paralogues in human: MIR33B (67% identical).